TSC1 (TSC complex subunit 1)
Description:
Non-catalytic component of the TSC-TBC complex, a multiprotein complex that acts as a negative regulator of the canonical mTORC1 complex, an evolutionarily conserved central nutrient sensor that stimulates anabolic reactions and macromolecule biosynthesis to promote cellular biomass generation and growth. The TSC-TBC complex acts as a GTPase-activating protein (GAP) for the small GTPase RHEB, a direct activator of the protein kinase activity of mTORC1. In absence of nutrients, the TSC-TBC complex inhibits mTORC1, thereby preventing phosphorylation of ribosomal protein S6 kinase (RPS6KB1 and RPS6KB2) and EIF4EBP1 (4E-BP1) by the mTORC1 signaling. The TSC-TBC complex is inactivated in response to nutrients, relieving inhibition of mTORC1. Within the TSC-TBC complex, TSC1 stabilizes TSC2 and prevents TSC2 self-aggregation. Acts as a tumor suppressor. Involved in microtubule-mediated protein transport via its ability to regulate mTORC1 signaling (By similarity). Also acts as a co-chaperone for HSP90AA1 facilitating HSP90AA1 chaperoning of protein clients such as kinases, TSC2 and glucocorticoid receptor NR3C1. Increases ATP binding to HSP90AA1 and inhibits HSP90AA1 ATPase activity. Competes with the activating co-chaperone AHSA1 for binding to HSP90AA1, thereby providing a reciprocal regulatory mechanism for chaperoning of client proteins. Recruits TSC2 to HSP90AA1 and stabilizes TSC2 by preventing the interaction between TSC2 and ubiquitin ligase HERC1.
Synonyms: KIAA0243; TSC; LAM; hamartin
Tractability: Antibody: UniProt places it where antibodies can reach, with high confidence; its Gene Ontology location is reachable by antibodies, with high confidence. PROTAC: UniProt records ubiquitination sites on it; ubiquitination databases record sites on it; its protein half-life has been measured.
Safety:
Unwanted effects reported when the protein is acted on. In parentheses: how it was acted on, where the effect was seen, and who reports it.
asthma (source: ClinPGx)
Gene: Protein-coding gene on chromosome 9 (132,891,348 to 132,946,874, reverse strand). Ensembl gene ENSG00000165699.
Subcellular location: Lysosome membrane; Cytoplasm, cytosol
Subcellular location (Human Protein Atlas): Cytosol; Basal body; Lipid droplets; Primary cilium transition zone
Pathways (Reactome):
Signal Transduction: Energy dependent regulation of mTOR by LKB1-AMPK; Inhibition of TSC complex formation by AKT (PKB)
Autophagy: Macroautophagy
Vesicle-mediated transport: TBC/RABGAPs
Gene Ontology:
Molecular function: ATPase inhibitor activity; Hsp70 protein binding; Hsp90 protein binding; protein binding; protein folding chaperone; protein-folding chaperone binding
Biological process: activation of GTPase activity; cell-matrix adhesion; cellular response to starvation; negative regulation of ATP-dependent activity; negative regulation of cell population proliferation; negative regulation of TOR signaling; negative regulation of TORC1 signaling; positive regulation of focal adhesion assembly; protein stabilization; regulation of cell-matrix adhesion; regulation of stress fiber assembly; response to insulin; adult locomotory behavior; cellular response to decreased oxygen levels; negative regulation of macroautophagy; regulation of cell cycle; protein folding
Cellular component: actin filament; cell cortex; cytoplasm; cytosol; lamellipodium; lysosomal membrane; membrane; protein folding chaperone complex; protein-containing complex; TSC1-TSC2 complex; nucleus; perinuclear region of cytoplasm; plasma membrane
Genetic constraint (gnomAD): Loss-of-function variants: 20 observed, 128.2 expected, observed/expected ratio (o/e) 0.16, 90% interval 0.11 to 0.23. The upper end of that interval is the gene's LOEUF score, 0.23, which puts it in group 1 of 6, group 1 being the genes least tolerant of losing a copy. Missense variants: 1,124 observed, 1,520.3 expected, observed/expected ratio (o/e) 0.74, 90% interval 0.7 to 0.78. Synonymous variants: 493 observed, 569.54 expected, observed/expected ratio (o/e) 0.87, 90% interval 0.8 to 0.93.
Cancer hallmarks: suppression of growth (promotes); escaping immune response to cancer; escaping programmed cell death (promotes); proliferative signalling (promotes); invasion and metastasis (suppresses); angiogenesis (promotes); tumour promoting inflammation (suppresses); escaping programmed cell death (suppresses); change of cellular energetics; angiogenesis (suppresses); tumour promoting inflammation; genome instability and mutations
Homologues: Orthologues: chimpanzee TSC1 (99% identical), macaque TSC1 (98% identical), dog TSC1 (90% identical), pig TSC1 (88% identical), guinea pig TSC1 (87% identical), mouse Tsc1 (87% identical), rat Tsc1 (86% identical), tropical clawed frog tsc1 (58% identical), zebrafish tsc1b (51% identical), zebrafish tsc1a (41% identical), Drosophila melanogaster Tsc1 (21% identical).
Diseases named in the same sentence as TSC1 in open-access papers:
TSC1 is named in the same sentence as 348 diseases in open-access papers, as found by Europe PMC text mining. Sharing a sentence is not in itself a finding about the gene and the disease. The quoted sentences say what the papers report.
tuberous sclerosis (349 papers, 2006 to 2026). Hereditary disease characterized by seizures, intellectual disability, developmental delay, and skin and ocular lesions. "Unfortunately, these drugs work on a specific cohort of tuberous sclerosis patients, harboring rare mutations in TSC1/TSC2, resulting in overactivating the PI3K-AKT–MTOR pathway." (PMID 40529445, 2025). "Tuberous sclerosis complex results from loss-of-function mutations in the TSC1 or TSC2 genes, which encode proteins crucial for tumor suppression." (PMID 39901197, 2025). "Tuberous sclerosis complex is an autosomal dominant monogenic disease, which is caused by the abnormal structure and function of TSC1/TSC2 complex caused by TSC1 or TSC2 mutation." (PMID 40595935, 2025). "The autosomal-dominant disorder observed in tuberous sclerosis complex (TSC) is caused by TSC1/2 loss-of-function mutations, which manifest in neurodevelopmental deficits, including profound hypomyelination and oligodendrocyte loss." (PMID 39995125, 2025). "Tuberous sclerosis complex is a genetic disorder characterised by the formation of benign tumours in multiple organs, primarily due to pathogenic variants in the TSC1 and TSC2 tumour suppressor genes." (PMID 40655946, 2025). "For over 20 years, significant progress has linked TSC1 or TSC2 gene mutations in stem cells to tuberous sclerosis complex symptoms." (PMID 39901197, 2025). "Tuberous sclerosis complex is a genetic disorder caused by mutations in the TSC1 or TSC2 genes, affecting multiple systems." (PMID 39901197, 2025). "Subependymal giant cell astrocytoma (SEGA) is a rare, low‐grade glioma typically associated with tuberous sclerosis (TS) and mutations in the TSC1 or TSC2 genes." (PMID 39492623, 2025). "Background and Clinical Significance: Tuberous sclerosis complex (TSC) is an autosomal dominant disorder caused by pathogenic variants in TSC1 or TSC2." (PMID 40722560, 2025). "Tuberous sclerosis a hereditary syndrome that is caused by alterations in the TSC1 (9q34) or TSC2 (16p13.3) genes, and it predisposes patients to several manifestations, including mental retardation, seizures, cardiac rhabdomyomas, and hamartomas." (PMID 38622693, 2024). "For example, IL-6 is significantly upregulated and plays a critical role in the development of tuberous sclerosis complex, a benign tumor syndrome caused by aberrant mTORC1 activation due to the loss of either TSC1 or TSC2." (PMID 38610018, 2024). "Tuberous sclerosis is mainly caused by TSC1 or TSC2 gene mutation, which leads to a series of clinical manifestations such as enhanced mTOR pathway activity and seizures." (PMID 39539663, 2024). "Tuberous sclerosis (TSC) is an autosomal dominant neurocutaneous syndrome resulting from mutations in the tumor suppressor genes TSC1 and TSC2." (PMID 39432612, 2024). "The Tuberous Sclerosis Complex, caused by mutations in the TSC1 or TCS2 genes, results in abnormalities in cell growth and differentiation through disruption of the mTOR (mammalian target of rapamycin) pathway." (PMID 39781307, 2024). "We report a family presenting classical tuberous sclerosis phenotype with an unusual, complex structural variant involving the TSC1 gene: an intrachromosomal inverted insertion in the long arm of chromosome 9." (PMID 38265426, 2024). "At the same time, loss-of-function mutations in either Tsc1 or Tsc2 genes, which are direct intracellular inhibitors of mTORC1, cause a genetic disorder named Tuberous Sclerosis Complex (TSC), characterized by the growth of benign tumors in multiple areas." (PMID 38531868, 2024). "Tuberous sclerosis complex (TSC) is a rare neurocutaneous disorder caused by heterozygous loss-of-function pathogenic variants in the tumour suppressor genes TSC1 and TSC2 encoding the tuberin and hamartin proteins, respectively." (PMID 39334956, 2024). "Tuberous sclerosis (TS) is a progressive neurodevelopmental disorder caused by mutations in Tsc1 or Tsc2 genes, leading to hyperactivity of the mTOR pathway." (PMID 39192595, 2024).
tuberous sclerosis (continued). "Tuberous Sclerosis (TS) is a rare, multisystem genetic disease caused by mutations in the TSC1 and TSC2 genes, leading to abnormalities in cell differentiation and proliferation." (PMID 38311784, 2024). "Tuberous sclerosis (TS) is a multi‐system, neurodevelopmental disorder caused by heterozygous mutations in either Tsc1 or Tsc2 genes, two negative regulators of mammalian target of rapamycin (mTOR) activity." (PMID 39192595, 2024). "Tuberous sclerosis complex results from inactivating mutations in the TSC1 or TSC2 genes, resulting in hyperactivation of the mTOR signaling pathway, which regulates cell growth, proliferation, survival, and autophagy." (PMID 37232723, 2023). "A good example is Tuberous Sclerosis Complex, a rare developmental disorder caused by mutations in TSC1 and TSC2." (PMID 37255597, 2023). "Tuberous Sclerosis Complex (TSC) is an autosomal dominant disorder that results in the loss of either the Tsc1 or Tsc2 gene." (PMID 38268565, 2023). "Tuberous Sclerosis Complex (TSC) is a syndrome caused by mutations in either the Tsc1 or Tsc2 genes." (PMID 38201256, 2023). "Tuberous sclerosis complex is considered to be caused by pathogenic mutations in the TSC complex subunit 1 (TSC1) or TSC2 gene and is unique in the similarity of clinical phenotypes between pathogenic mutations in the two genes." (PMID 36732866, 2023). "Tuberous sclerosis (TSC) has been reported to be an inheritable disease resulting from mutations in either the TSC complex subunit 1 (TSC1) or 2 (TSC2) genes." (PMID 36539038, 2023). "In detail, patient #12 was diagnosed with tuberous sclerosis due to multiple Hypomelanotic macules throughout the body, multiple calcified subependymal nodules revealed by head CT, and a novel TSC1 pathogenic variant revealed by whole exome sequencing." (PMID 37153594, 2023). "Subependymal giant cell tumors are well-known manifestations of tuberous sclerosis caused by alterations in TSC1 or TSC2, and the pathogenic activation of mTOR leads to tumor development." (PMID 37221626, 2023). "Tuberous sclerosis complex (TSC) is caused by mutations in the Tsc1 or Tsc2 genes, whose products form a complex and inactivate the small G-protein Rheb1." (PMID 36606143, 2022). "Up to 90% of patients with tuberous sclerosis from TSC1/2 mutations will develop epilepsy, with two-thirds of cases being medication-resistant." (PMID 35250833, 2022). "Tuberous sclerosis complex, an autosomal dominant disorder, characterized by mutations in TSC1 or TSC2, causes hamartoma formation in various of the organ systems." (PMID 36231025, 2022). "Tuberous sclerosis complex is characterized by a mutation in TSC1 or TSC2 which activates the signal pathway of mTORC1/RUNX1/EGFR with loss of function." (PMID 36231025, 2022). "Rodent studies have shown that loss of Tsc1/2 function in tuberous sclerosis impacts multiple processes at different developmental stages, including neuronal morphology and migration, synaptic plasticity and glial function." (PMID 36340790, 2022). "Germline heterozygous mutations in TSC1 are known to be responsible for hamartoma syndromes, including tuberous sclerosis (TS) that confer increased susceptibility to renal cancer." (PMID 34067022, 2021). "Inactivating mutations in either TSC1 or TSC2 cause Tuberous Sclerosis Complex, an autosomal dominant disorder, characterized by multi-system tumor and hamartoma development." (PMID 33891611, 2021). "Mutations of TSC1 or TSC2 genes cause tuberous sclerosis, an autosomal dominant genetic disease characterized by the development of histologically diverse hamartomas or benign tumors, including skin, brain, and kidneys." (PMID 33436626, 2021). "One example is that NCCN guideline recommends everolimus as a systemic therapy for patient with tuberous sclerosis syndrome, which is often characterized with TSC1/2 germline mutations." (PMID 34926252, 2021).
tuberous sclerosis (continued). "In patients with tuberous sclerosis complex suffering from severe and treatment-resistant epilepsy, the mTOR pathway is hyperactivated due to mutations in TSC1 and TSC2 genes." (PMID 33859552, 2021). "Tuberous sclerosis (TSC) is an autosomal dominant genetic disorder in which mutation of TSC1 or TSC2 genes leads to increased activation of the mammalian target of rapamycin (MTOR) pathway." (PMID 33897576, 2021). "Tuberous sclerosis, another common cause of syndromic ID, is associated with increased risk of brain tumor due to mutations of TSC1 and TSC2." (PMID 34673770, 2021). "Heterozygous mutations in either TSC1 or TSC2 that form an MTOR-inhibiting complex can cause tuberous sclerosis by hyperactivating MTOR signaling." (PMID 34200511, 2021). "Mutation of TSC1 is associated with tuberous sclerosis complex, an autosomal dominant multisystem disorder that affects the brain, skin, heart, kidneys, and lung." (PMID 34957217, 2021). "Tuberous sclerosis complex is caused by mutations in genes TSC1 and TSC2 that encode hamartin and tuberin and is involved in the control of cell division and growth in the body." (PMID 34830686, 2021). "Pathogenic TSC1 variants lead to tuberous sclerosis, which is characterized by skin abnormalities, developmental delay, epilepsy and behavioural problems such as ADHD and ASD." (PMID 34680906, 2021). "In this study, we detected a novel TSC1 frameshift mutation c.1550_1551del (p.Arg517GlnfsTer17) from two members of a Chinese family diagnosed as tuberous sclerosis." (PMID 32735081, 2020). "The majority of cases of tuberous sclerosis occur due to pathogenic mutations in TSC2 (encodes for tuberin) whilst TSC1 (encodes for hamartin) and other rare mutations account for remaining cases." (PMID 33409061, 2020). "Among these, TSC1 or TSC2 characterizes rare subependymal giant-cell astrocytomas in patients with tuberous sclerosis, causing aberrant activation of mTOR." (PMID 33747896, 2020). "Intriguingly, hyperactivation of the mTORC1 pathway, is a hallmark of Tuberous Sclerosis (TSC) in patients as well Tsc1 or Tsc2 knockout mouse models, that present with a range of neurological disorders including epilepsy, relevant to NCL pathology." (PMID 31655107, 2020). "Tsc1/Tsc2 promotes axonal growth via the upregulation of SAD kinase in tuberous sclerosis complex, which is characterized by tumor predisposition and neurological abnormalities, including epilepsy, mental retardation, and autism." (PMID 32267308, 2020). "Hypofunctional mutations in TSC1 or TSC2 in tuberous sclerosis result in the uncontrolled activation of the mTORC1 pathway and subsequent inhibition of autophagy directly linked to epileptogenesis in a forebrain-specific conditional TSC1 mouse model." (PMID 32231521, 2020). "Only one of ten APEs with TSC1 or TSC2 variants had clinical presentations fitting the diagnostic criteria of tuberous sclerosis complex." (PMID 31875159, 2019). "mTORC1 abnormal activation induced by mutations of TSC1 or TSC2 contributes to the development of the genetic disorder tuberous sclerosis complex (TSC), which is defined by benign hamartomas in several organ systems." (PMID 31088250, 2019). "Tuberous sclerosis, a mutation in TSC1/2, produces an autosomal dominant genetic disorder, characterized by benign hamartomas in multiple organ systems." (PMID 31088250, 2019). "For example, thus far cystic fibrosis had only been associated with variants in CFTR, while tuberous sclerosis had only been associated with TSC1 and TSC2." (PMID 30987386, 2019). "SEGAs are tumors frequently arising in patients with tuberous sclerosis complex that have activated mTORC1 signaling due to mutations frequently affecting the TSC1 or TSC2 genes." (PMID 31510109, 2019). "For example, in patients with a clinical diagnosis of tuberous sclerosis, a spectrum of heterozygous variants affecting TSC1 and TSC2 had been described." (PMID 30987386, 2019).